STAT6 (signal transducer and activator of transcription 6)
Diseases named in the same sentence as STAT6 in open-access papers (continued):
Sharing a sentence is not in itself a finding about the gene and the disease.
eczema (4 papers, 2008 to 2025). "The current study investigated the association of SNPs in IL13 (rs20541) and STAT6 (rs1059513) genes separately and jointly (gene-gene interaction) on the risk for eczema in two independent population-based studies." (PMID 23815671, 2013). "In the IOW study, the homozygous genotype for the minor allele CC of STAT6 rs1059513 was significantly associated with eczema in the repeated measurements analysis when compared to the non-risk genotype TT (RR = 2.21; 95% CI: 1.05 – 4.66)." (PMID 23815671, 2013). "Our investigation demonstrates an important combined effect of genetic variants within IL13 and STAT6 genes on eczema risk." (PMID 23815671, 2013). "Our search of the literature indicated a lack of studies investigating the possible interaction between genetic variants in IL13 and STAT6 genes in relation to eczema risk." (PMID 23815671, 2013). "Log-binomial regressions were applied to (i) account for the interaction between IL13 (rs20541) and STAT6 (rs1059513) polymorphisms and (ii) estimate the combined effect, in terms of risk ratios (RRs), of both risk factors on the risk of eczema." (PMID 23815671, 2013). "The current study demonstrates that gene-gene interaction (epistasis) between IL13 and STAT6 polymorphisms contributes significantly to the genetic determination of eczema in two independent British epidemiological studies." (PMID 23815671, 2013). "Our aim was to investigate whether SNPs in IL13 and STAT6 genes, which share a biological pathway, have an interactive effect on eczema risk." (PMID 23815671, 2013). "However, a consistent significant statistical interaction under a dominant genetic model between IL13 (rs20541) and STAT6 (rs1059513) on the risk of eczema was demonstrated in both studies." (PMID 23815671, 2013). "The purpose of this study was to determine whether an interaction between rs20541 in IL13 and rs1059513 in STAT6 on eczema risk exists." (PMID 23815671, 2013). "In the discovery step, to determine whether IL13 (rs20541) and STAT6 (rs1059513) SNP genotypes have an interactive effect on the risk for eczema, four genetic models (co-dominant, dominant, recessive, and additive) were used to test for statistical interaction (IL13 × STAT6) in the IOW study." (PMID 23815671, 2013). "Both MTMZM and Pevisone can alleviate the symptoms of eczema, promote the recovery of skin lesions, reduce inflammation factors, and reduce the level of proteins associated with P38/NF-κB and JAK1/STAT6 pathways." (PMID 40933470, 2025). "This study adds to the current knowledge of genetic susceptibility by demonstrating for the first time an interactive effect between SNPs in IL13 (rs20541) and STAT6 (rs1059513) on the occurrence of eczema in two independent samples." (PMID 23815671, 2013). "Our study adds to the current knowledge of genetic susceptibility by demonstrating for the first time an interactive effect between SNPs in IL13 (rs20541) and STAT6 (rs1059513) on the occurrence of eczema in two independent samples." (PMID 23815671, 2013). "Th2 cytokines, such as IL-13 and transcription factor STAT6 are key elements in the inflammatory response that characterize allergic disorders, including eczema." (PMID 23815671, 2013). "Hence, altered STAT6 activation may contribute to the major hallmarks of eczema: (i) allergic sensitization and (ii) impaired epidermal barrier." (PMID 23815671, 2013). "This study aims to explore the therapeutic effect of MTMZM on rats with eczema and its influence on P38/NF-κB and JAK1/STAT6 pathway." (PMID 40933470, 2025). "Similarly, there was no main effect of STAT6 SNP rs1059513 and eczema in the dominant model in either population." (PMID 23815671, 2013).
Ewing sarcoma (4 papers, 2022 to 2024). A small round cell tumor that lacks morphologic, immunohistochemical, and electron microscopic evidence of neuroectodermal differentiation. "Taken together, these data support the notion that STAT6 contributes to Ewing sarcoma chemotherapy resistance, in part, by regulating GAS6 transcription." (PMID 38906855, 2024). "Our identified chemotherapy-induced JAK1/STAT6/GAS6/TAM signaling contribution to chemoresistance in cancer warrants study beyond Ewing sarcoma." (PMID 38906855, 2024). "However, due to the small number of patients in this study, we cannot conclude if increased JAK1/STAT6 expression contributes to Ewing sarcoma chemoresistance." (PMID 38906855, 2024). "Using phospho-profiling, genetic, and biochemical approaches, our studies unravel a chemotherapy-induced mechanism for JAK1/STAT6/GAS6-mediated autocrine or paracrine signaling contributing to Ewing sarcoma chemoresistance, by activating TAM kinases and subsequent downstream Akt and ERK signaling." (PMID 38906855, 2024). "Our study reveals the chemo/JAK1/STAT6 signaling also promotes GAS6 transcription and secretion in Ewing sarcoma." (PMID 38906855, 2024).
heart failure (4 papers, 2012 to 2020). Inability of the heart to pump blood at an adequate rate to meet tissue metabolic requirements. "Taken together, these results provide novel evidence that STAT6 signal is a potential target for the treatment of myocardial fibrosis and heart failure after ISO-induced myocardial injury." (PMID 33192584, 2020). "STAT6 should be a promising cardioprotective target against myocardial fibrosis and heart failure after β1-AR overactivation–induced myocardial injury." (PMID 33192584, 2020). "Additional studies will be needed to address whether the histamine-STAT6 axis could be a useful therapeutic target for the treatment of MI-induced heart failure." (PMID 28272448, 2017). "Thus, our data indicated that the histamine-STAT6 axis may be a potential target for preventing MI-induced cardiac remodeling and heart failure." (PMID 28272448, 2017). "Moreover, STAT4 levels were significantly higher than STAT6 levels in the heart failure group." (PMID 22811738, 2012). "At any event, STAT4 mRNA was overexpressed in CCC patients with heart failure as compared with STAT6 levels in patients with presence or absence of heart failure, a further indication of TH1 signaling." (PMID 25152568, 2014).
Hyperglycemia (4 papers, 2017 to 2026). An increased concentration of glucose in the blood. "Interestingly, we found that hyperglycemia inhibited IL-10-secreting M2-like macrophage polarization, as revealed by decreased Arg1 and Mrc1 gene induction accompanied by a decrease in STAT3 and STAT6 signaling pathway activation." (PMID 29081777, 2017).
influenza (4 papers, 2018 to 2025). An acute viral infection of the respiratory tract, occurring in isolated cases, in epidemics, or in pandemics; it is caused by serologically different strains of viruses (influenzaviruses) designated A, B, and C, has a 3-day incubation period, and usually lasts for 3 to 10 days. "Here, we tested whether STAT6 signaling is altered due to increased IL-4 levels in Stat2−/− mice during influenza-bacterial super-infection." (PMID 30337919, 2018). "This is also in agreement with the low production of IL-4 during early influenza infection, and thus, a lack of STAT6-dependent induction of Pparg gene." (PMID 36052067, 2022).
injury (4 papers, 2020 to 2023). Damage inflicted on the body as the direct or indirect result of an external force, with or without disruption of structural continuity. "For example, signal transducer and activator of transcription 6 (STAT6) (located in the tnf-α 2 subregion) were reported to mediate neuroinflammation caused by ethanol in mice with a traumatic brain injury." (PMID 34220336, 2021). "In conclusion, MCTR1 promotes resident M2 alveolar macrophage polarization via the STAT6 pathway to accelerate resolution of LPS‐induced lung injury." (PMID 32757380, 2020). "Our findings revealed that STAT6 is a pivotal regulator of ferroptosis, which may be a potential therapeutic target for the treatment of acute lung injury." (PMID 35668064, 2022).
lung adenocarcinoma (4 papers, 2018 to 2024). A carcinoma that arises from the lung and is characterized by the presence of malignant glandular epithelial cells. "This indicates that GM-CSF secretion from lung adenocarcinoma cells can stimulate the activation of STAT3/STAT6 signaling pathway in TAM and promote the secretion of cathepsin, which is exacerbated by the inhibition of SHP2." (PMID 38747738, 2024). "We previously found high-level expression of STAT6 in human lung adenocarcinoma and squamous cell carcinoma, specifically in infiltrated immune cells located in the lung interstitium." (PMID 31798581, 2019). "Within the lung adenocarcinoma and squamous carcinoma tissues, STAT6 expression is higher in interstitial cells than that in epithelial cells." (PMID 31798581, 2019). "HGF treatment increased STAT6 Y641 phosphorylation in both A549 (lung adenocarcinoma) and A431 (epidermoid) cancer cell lines following stimulation with hHGF." (PMID 29771943, 2018). "This study proposes that SHP2 may dampen lung adenocarcinoma progression by inhibiting the STAT3/STAT6 pathway in TAMs, consequently reducing M2 polarization and the secretion of factors like cathepsin, which in turn, could limit the growth and spread of lung adenocarcinoma cells." (PMID 38747738, 2024). "We assess the effect of lung adenocarcinoma cells on TAM through detecting the expression of SHP2, p- STAT1, p-STAT3, p-STAT5, p-STAT6, IL-4, IL-10, Cathepsin-L, Cathepsin-S, Cathepsin-K and Arginase-1 in each group of THP1 cells cocultured with and without A549 cells by western blot." (PMID 38747738, 2024). "Both of epithelial and stromal components were negative with estrogen and progesterone receptors, STAT6, and marker for adenocarcinoma of the lung (MAdL)." (PMID 32193604, 2020).
malaria (4 papers, 2010 to 2025). Malaria is a serious and sometimes fatal disease caused by a parasite that commonly infects a certain type of mosquito which feeds on humans. "IgE antibodies have been shown to have a pathologic role in malaria infection and STAT-6 has been implicated in malaria pathogenesis, shown to influence severity of the disease." (PMID 40007543, 2025). "To answer these questions, we evaluated the genetic variability of CD209 (rs4804803), CD28 (rs35593994) and STAT6 (rs3024974) single nucleotide polymorphisms among malaria-infected children in Nigeria and extrapolated any association with markers of infection." (PMID 31979279, 2020). "The study indicated that the STAT6 promoter polymorphism rs3024944 was associated with uncomplicated malaria, whereas the FOXP3 promoter variant rs11091253 was associated with significant P. falciparum parasitaemia levels." (PMID 23297791, 2013). "The minor allele rs3024944C of STAT6 gene was associated with decreased risk of clinical uncomplicated malaria (Adjusted OR: 0.57, 95%CI: 0.35-0.91, P=0.019)." (PMID 23297791, 2013). "The genotypic frequencies of STAT6, CD28 and CD209 gene promoter polymorphisms in malaria patients were compared to the control group with logistic regression analysis." (PMID 31979279, 2020). "We genotyped blood samples collected from a total of 561 individuals (231 malaria-infected patients and 330 uninfected, control individuals) for STAT6 (rs3024974), CD28 (rs35593994) and CD209 (rs4804803) gene polymorphisms using Taqman SNP genotyping assays." (PMID 31979279, 2020). "The prevalence of rs3024944CC genotype of STAT6 was significantly higher in the group of asymptomatic children compared to that of uncomplicated malaria (P=0.003)." (PMID 23297791, 2013). "This is the first study that shows the correlation between a promoter SNP STAT6 rs3024944 and protection against uncomplicated malaria." (PMID 23297791, 2013). "To summarize, selected regulatory SNPs in the promoter region of FOXP3, IL10RA, IL10RB, STAT6 and TNFRSF18 genes have been investigated for possible association with uncomplicated malaria and high P. falciparum parasite density among Congolese children." (PMID 23297791, 2013). "Our inheritance test model revealed that the STAT6 (rs3024974) gene polymorphism did not increase the risk of malaria with the dominant (G/A-A/A versus G/G; OR = 0.98; 95% CI = 0.67–1.44) or recessive allele (G/G-G/A versus A/A; OR = 0.62; 95% CI = 0.32–1.20)." (PMID 31979279, 2020). "Likewise, the STAT6 gene is known to regulate the expression of regulatory T cells, while potentially modulating the immune response to malaria." (PMID 31979279, 2020). "Association analysis revealed that genotype rs3024944CC of STAT6 gene was observed more in children who did not have clinical malaria episode during the follow up (asymptomatic group) compared to uncomplicated malaria group (Adjusted OR: 0.17, 95%CI: 0.05-0.55, P=0.003)." (PMID 23297791, 2013). "It is also interesting to note that another member of STAT family (i.e. STAT6) could be involved in mediating erythropoietic suppression during acute blood-stage malaria and that interleukin-4 (in 5q31–q33 region) and possibly interferon-γ could also play a role in this mechanism." (PMID 20657648, 2010). "However, the gene expression levels of the M2 transcription factor, STAT-6 and the angiogenic factors ANG-1, were significantly lower in the placenta from malaria-positive women." (PMID 40007543, 2025). "For STAT-6, there was a significant decrease (P = 0.0116) in malaria positive women compared to malaria negative women, corroborating the role of this factor in pathogenesis of human malaria." (PMID 40007543, 2025). "Our data suggest that CD209 (rs4804803) is a susceptibility factor for clinical malaria that also influences disease pathogenesis, but not CD28 (rs35593994) or STAT6 (rs3024974)." (PMID 31979279, 2020).
malaria (continued). "Our results show significant differences in genotypic frequencies between malaria and control groups for CD28 (rs35593994; p = 0.0001) and CD209 (rs4804803; p = 0.0001) but not STAT6 (rs3024974; p = 0.30) gene polymorphisms." (PMID 31979279, 2020). "Real time PCR was used to quantify the relative expression of STAT-1 and IRF-5, critical transcription factors for M1 polarization, and STAT-6 and c-Maf, salient factors for M2 polarization, in placental macrophages, and compared between malaria positive and negative women." (PMID 40007543, 2025). "In total, five different haplotypes were observed for STAT6 locus, of which the major haplotype CGG was marginally significant with more prevalence among children who presented at least one clinical episode (uncomplicated malaria) (Adjusted OR: 1.4, 95%CI: 1.0-2.0, P=0.05)." (PMID 23297791, 2013). "However, it is not impossible that STAT6 (rs3024974) and CD28 (rs35593994) polymorphisms may mediate malaria pathogenesis through a different mechanism not examined in this study." (PMID 31979279, 2020).
meningeal tumor (4 papers, 2013 to 2022). "However, no meningeal tumor nor Stat6 translocation was identified in our case." (PMID 26351605, 2015).
metastatic disease (4 papers, 2017 to 2021). "Eventually, STAT6 acts as a pre-cancerous factor in PCa, promoting progression to metastatic disease." (PMID 34638338, 2021). "STAT6 was predominantly expressed in the nuclei of the metastatic tumor cells but rarely in the primary tumors." (PMID 30218063, 2018). "In addition, a higher percentage of phosphorylated STAT6 (detected by proximity ligation assay) was found in the metastatic head and neck cancer samples, suggesting the activation of STAT6 in the metastatic tumors." (PMID 30218063, 2018). "Consistent with the ALK staining, p-JAK2 was present only in the metastasis of these three cases, and p-STAT6 staining did not appear in any metastatic tumors." (PMID 34090412, 2021).
nematode infection (4 papers, 2009 to 2018). "In fact, IFNγ production and T. muris worm burdens in wild-type mice kept outdoors for the short term were nearly as high as those of STAT6-/- mice that are genetically susceptible to nematode infection." (PMID 29518091, 2018). "The expression of these worm-clearing cytokines is promoted by a transcription factor, signal transducer and activator of transcription 6 (STAT6), and mice deficient in STAT6 (STAT6-/-) are highly susceptible to nematode infections." (PMID 29518091, 2018). "Since immunity to the related gastrointestinal nematode parasite N. brasiliensis is also highly dependent on IL-4R/Stat6/IL-13-dependent signaling, we examined whether resistance to nematode infection in the small intestine was affected by Retnla deficiency." (PMID 19381262, 2009). "It is known that IL-13 activation of STAT6 during nematode infection increases the expression of IL-13Rα2, 5-HT2A, and arginase I in WT." (PMID 23536877, 2013). "STAT6 is a master transcription factor important for type 2 immunity and is involved in host defense against nematode infection and development of allergic inflammation." (PMID 23536877, 2013). "Interestingly, the production of IL-25 following nematode infection is itself dependent on IL-4Rα, mediated by IL-13 activation of STAT6." (PMID 30238872, 2018).
osteosarcoma (4 papers, 2017 to 2025). A usually aggressive malignant bone-forming mesenchymal neoplasm, predominantly affecting adolescents and young adults. "In this case, although the initial diagnosis was osteosarcoma, a re-examination that included immunohistochemical detection of STAT6 and RT-PCR detection of the NAB2 exon 6-STAT6 exon 16 fusion led us to confirm a diagnosis of malignant SFT." (PMID 28494796, 2017). "Immunohistochemical STAT6 staining is very useful for distinguishing SFTs from other neoplasms, such as osteosarcoma." (PMID 28494796, 2017).
Pneumocystis infection (4 papers, 2019 to 2023). "Regarding this, we have recently documented that kaempferol, a STAT6 pathway inhibitor, was associated to partial reduction of levels of mucins during Pneumocystis infection." (PMID 31170201, 2019). "There is evidence that relates Pneumocystis infection and STAT6 pathway induction leading mucus increment via transcriptional repression/activation of mucin genes." (PMID 37108906, 2023). "Despite various pathways that could explain the increment of mucus in our animal model, evaluation of STAT6-dependent transcription factors was chosen because of previous data showing STAT6 pathway activation in Pneumocystis infection rat models." (PMID 37108906, 2023). "Induction of the CLCA1 pathway with increased mucins has been shown to correlate with Pneumocystis infection in humans and in animal models and is strongly related to IL-13 driven mucus cell metaplasia, STAT6 activation and MUC5AC and MUC5B expression in the airways." (PMID 31333624, 2019).
sarcoidosis (4 papers, 2020 to 2025). Sarcoidosis is a multisystemic disorder of unknown cause characterized by the formation of immune granulomas in involved organs. "Pretreatment of PBMCs with STAT-6 inhibitors significantly decreased granulomatous nodules and M2 polarization, which provided a novel strategy to clarify the role of M2 macrophages in sarcoidosis." (PMID 39904950, 2025). "STAT6 activation is an important downstream mediator of IL4/IL13 responses in these cells, supporting its role in driving alternative (M2) macrophage activation in sarcoidosis." (PMID 40521183, 2025).
visceral leishmaniasis (4 papers, 2012 to 2018). A severe form of leishmaniasis characterized by irregular bouts of fever, substantial weight loss, swelling of the spleen and liver, and anemia (which may be serious). "In a hamster model of visceral leishmaniasis (VL), Osorio and colleagues showed that Leishmania donovani infected macrophages displayed enhanced STAT6 and STAT3 signalling in response to the growth factors FGF2 and IGF1, further enhanced by co-stimulation with IL-4 or IL-10." (PMID 29352310, 2018). "In experimental visceral leishmaniasis, IGF-I increases the expression of arginase, while the deletion of IGF-IR leads to decreased arginase in a STAT-6-dependent mechanism and restriction of L. donovani growth." (PMID 30150896, 2018).